IFNG (interferon gamma)
Diseases named in the same sentence as IFNG in open-access papers (continued):
Sharing a sentence is not in itself a finding about the gene and the disease.
infection (continued). "Alternatively, since inflammation contribute to S. pneumoniae proliferation in lungs and NK cell activity and IFNγ could enhance inflammation, the lesser contribution of NCR1-deficient NK cells to inflammation could oppose the picture in the later stages of the infection." (PMID 21887255, 2011). "Comparable IL-12p70 and IFNγ concentrations were found in the lung of WT mice and Tm-TNF mice 133 days post-infection." (PMID 22132068, 2011). "Prior to infection protectively vaccinated mice exhibit augmented CD4 and CD8 IFNγ and memory responses as well as decreased IL-10 and IL-13 responses." (PMID 21695103, 2011). "Similar to the immune responses analyzed in the spleen, IFNγ and TNFα production by LCMV-specific CD4+ T cells was reduced or even absent in the liver of CD8-depleted mice on day 8 and 11 after infection." (PMID 21966366, 2011). "An efficient cellular immune response with IFNγ-secreting CD4+ and CD8+ T cells is responsible for the decrease of P. brasiliensis in the organs during experimental infection." (PMID 21249212, 2011). "The distribution and intensity of FIV infection and IFNγ transcription differed between single and co-infected cats, characterized by higher FIV proviral loads and IFNγ expression in co-infected cat tissues." (PMID 22069521, 2011). "Cells expressing all 3 functional markers were maintained and the total IFNγ+ CD8 T cell response remained above the baseline measurement even two and a half months post-infection." (PMID 22132212, 2011). "As the infection in vivo propagates through amastigotes which lack LPG, we asked the question if their role in IFNγ signaling inhibition was different from that of promastigotes." (PMID 21931549, 2011). "The frequency of IFNγ+ CD4+ T cells increased in the later stages of infection and by d28 pi, 39.1% of CD4+ T cells in the liver and 7.6% in the spleen of WT mice were producing IFNγ." (PMID 21253574, 2011). "Based on our previous report, C. pneumoniae-induced secretion of the cytokines TNF and IFNγ and the chemokines KC and MCP-1 depended on MyD88 three days post infection." (PMID 22096480, 2011). "Nevertheless, it was previously reported that LVS-infected IL-12p35−/− mice, which fail to mount a robust IFNγ response, were still able to clear intradermal LVS infection." (PMID 20585449, 2010). "A strong T helper 1 response is characteristic of S. Typhimurium infection in the mouse, with a large expansion in numbers of activated IFNγ-secreting CD4+- and CD8+-T cells in the blood, though this response takes a week to develop during primary infection." (PMID 21048923, 2010). "TNFα protein levels increased steadily from day 2 through day 29 post-infection while IL6 and IFNγ protein levels peaked at day 9, before reducing to levels seen in mock infected animals." (PMID 20386712, 2010). "Immunization with the same antigen during the postnatal life increased antigen-specific recall interferon gamma (IFN-γ) responses and protection against infection." (PMID 20300629, 2010). "While STAT1−/− infected mice showed a similar trend of increased transcript levels at day 2, expression levels of IFNγ and MCP1 continued to increase through day 9 post-infection." (PMID 20386712, 2010). "This is characterized by the recruitment of highly activated T-lymphocytes and macrophages to the lungs, and expression of IFNγ, TNF, cytokine and chemokine signaling pathways, four weeks post-infection." (PMID 20824205, 2010). "Interferon gamma (IFN-γ) and tumor necrosis factor (TNF) are the key cytokines of the murine host response, and are absolutely required to control infection." (PMID 19543527, 2009). "To illustrate the scale of the phenomenon, we prepared a simple overview image of IFNγ-induced fibroblasts infected 8 hours previously with T. gondii ME49 strain at a MOI of 5 and washed free of floating T. gondii at 2 hours after infection." (PMID 19197351, 2009).
infection (continued). "In IFNγ-treated cells, T. gondii PVs coated with IRG proteins became disrupted during the first few hours after infection." (PMID 20368812, 2009). "A significant increase in CCR5, CCL5, and IFNγ gene expression in the spleen and ILN was observed 7 days after genital infection when compared with levels before infection." (PMID 18700040, 2008). "This was associated with reduced anti-parasitic CD4+ T cell activation in the spleen and lowered hepatic IFNγ, TNF and nitric oxide production by 14 days post infection." (PMID 18802456, 2008). "One case presentation describes a successful treatment with recombinant interferon gamma (INF-gamma) together with antimicrobial therapy, which led to clearance of infection in a chronically relapsing patient." (PMID 18522718, 2008). "Interferon-gamma (IFN-γ) is a potent pro-inflammatory cytokine that regulates a spectrum of biological processes, and is produced primarily in response to infection." (PMID 17032459, 2006). "In B6 mice 42 d after infection, PMA and ionomycin treatment induced a significant percentage of CD8 T cells to express IFNγ, TNFα, or both cytokines." (PMID 16733540, 2006). "One of the key responses initially induced by IFNγ in macrophages is the release of the chemokines CXCL9, CXCL10 and CXCL11, which attract additional T-lymphocytes and other immune cells from the bloodstream to the focus of infection." (PMID 40762872, 2025). "To analyze further functional states of THP-1 cells, which might influence the sensitivity for TcpC during an infection with CFT073, we polarized THP-1 cells to M1 and M2 macrophages using PMA/IFNγ/LPS or PMA/IL-4/IL-13, respectively." (PMID 41310197, 2025). "This cytokine is stimulated by IFNγ, which was not significantly correlated with infection duration." (PMID 39836629, 2025). "Consistent with our expectations, OT-I T cells primed by ΔActA-Lm-OVA infection in the absence of IFNγ were significantly biased towards MPECs when compared to OT-I T cells primed in WT mice." (PMID 40163479, 2025). "infection did not change the levels of cytokines interleukin 1β (IL-1β), IL-6, IL-10, interferon gamma (IFN-γ), and tumor necrosis factor alpha (TNF-α)." (PMID 40302747, 2025). "Following infection of the central nervous system (CNS), microglia and astrocytes become hyperactivated, releasing excessive proinflammatory cytokines such as tumor necrosis factor-alpha (TNF-α) and interferon-gamma (IFN-γ)." (PMID 40760662, 2025). "In an experimental infection of horses using virus mutants with multiple deletions, including ORF1 and ORF71, it was reported that CD8+ and INFγ-positive cells were dominant, whereas CD4+ and IFNγ-positive cells remained lower throughout the study." (PMID 39852824, 2025). "Interestingly, while the levels of Hgf remained unchanged in the 4T1 group, they were reduced following infection, but subsequently upregulated by SFV/IFNγ." (PMID 40547518, 2025). "In addition, J774A.1 macrophages were infected with H37Rv (multiplicity of infection [MOI] = 5), and the mRNA expression of cytokines TNF-α, IL-2, IL-12, and IFNγ was detected, which was consistent with the results of LPS treatment." (PMID 40396746, 2025). "Subsequent analysis confirmed that IFNγ signaling in IEC does not affect bacterial burden but instead is critical in driving intraepithelial lymphocytes to restrain infection-induced inflammation." (PMID 39937862, 2025). "IFNα, IFNβ, and Universal type I IFN treatment decreased infection in the NT cells while IFNγ had no significant impact." (PMID 41385587, 2025). "IFNγ and TNF, which are produced by CD4+ effector T lymphocytes, are believed to be the main cytokines responsible for macrophage activation at the site of infection in TB." (PMID 40724823, 2025). "The central function of IFNγ is to augment the immune response upon infection with nonviral pathogens, and IRF1 deficiency in macrophages causes severe mycobacterial, but not viral, disease in humans." (PMID 39773901, 2025).
infection (continued). "We hypothesized that removal of IFNγ from the host would increase MPEC formation in both infections and improve the persistence of OT-I T cells after PbA infection." (PMID 40163479, 2025). "However, during the course of infection, these usually well-correlated Th1 cytokines show alternating patterns in IE upregulation of SPP1 contrasted by the L upregulation of IFNG." (PMID 39863683, 2025). "Furthermore, a recent report has shown that infection with SARS-CoV-2 leads to increased HLA-E expression in lung cells, which in turn results in enhanced degranulation, IFNγ production and target cell cytotoxicity in NKG2C+ adaptive-like NK cells." (PMID 40358152, 2025). "Post-infection, MAIT cells are highly sensitive to microbial metabolites and inflammatory cues, driving robust secretion of interferon-gamma (IFN-γ), which could contribute to sustained inflammation." (PMID 41516190, 2025). "On the other hand, IFNγ may induce macrophages to release chemokines CXCL9, 10, and 11 to attract B and T lymphocytes to the sites of infection." (PMID 40762872, 2025). "For example, at 11 DoA (4 days post infection), TLR4 and CSF2RA expressions were correlated to Enterococcus and IL18 (a pro-inflammatory cytokine known for its ability to enhance the production of interferon-gamma) to Salmonella." (PMID 40079593, 2025). "Notably, the expression of TLR2 and TLR4 on ECs can be modulated in response to infection and inflammatory stimuli, either directly through exposure to lipopolysaccharide (LPS) or indirectly through cytokines such as TNF-α and interferon-gamma (IFN-γ)." (PMID 41268545, 2025). "Adenovirus 5 was used as a delivery vehicle by Brazilian scientists; these studies showed that prophylactic Ad-ASP2/Ad-TS elicited robust type 1 cytokines (TNFα, IFNγ) producing CD8+ effector T cell response and 100% survival from lethal challenge infection in Balb/c and C57BL/6 mice." (PMID 40005501, 2025). "This γδ T stimulation seems to be necessary but not sufficient to induce a protective phenotype because vaccination with the ∆gmt2/∆sgl1 does not induce any protection against a secondary infection, despite similar IFNγ stimulation to the other two strains." (PMID 40298449, 2025). "We also demonstrated that B cells, IFNγ, TLR signaling through the MyD88 adaptor protein, and iNOS2 production of NO were dispensable for the control of infection, though clearance of the parasite was moderately delayed in mice lacking B cells and IFNγ-/- mice." (PMID 39452729, 2024). "Furthermore, CD8+ T cells also produce cytokines such as IFNγ and TNF, which recruit neighbouring immune cells to the site of infection to assist in viral clearance." (PMID 38362528, 2024). "With IFNγ blockade, genes in cluster 2, including IL18R1, IDO1, CXCL11, CD274 (PD-L1), and PTPN2, were similarly expressed at day 3 post-infection but were more highly expressed at day 7 compared to controls and had increased expression over the day 3 timepoint." (PMID 38950078, 2024). "A. marginale-specific CD4+ T cell responses are functionally impaired throughout infection as indicated by diminished antigen-specific T cell proliferation and IFNγ producing cells and the absence of long-term memory." (PMID 38596123, 2024). "In support of this, stimulation of murine macrophages with interferon-gamma (IFN-Υ) prior to the infection increases RNS production and the proportion of non-growing Salmonella." (PMID 38421944, 2024). "This analysis prompted us to envision the presence of CD44hi CCR6+ IL17-committed γδ T cells in C2, and NK1.1+ IFNγ/IL-4-committed γδ T cells in C7, both unaffected by infection, suggesting their absence of response to CMV." (PMID 38976755, 2024). "We next examined whether these IFNε-mediated effects on NK cell number, activity, and IFNγ production are specific to the FRT or are also systemic, both at baseline and during infection." (PMID 38263527, 2024).
infection (continued). "BM-MoDCs treated with IFNγ alone or IFNγ and Pam3CSK4 efficiently restricted T. gondii growth by 14 h post-infection; however, TLR2 stimulation alone was not sufficient for parasite clearance." (PMID 38538595, 2024). "Transcripts for c-Myc, Myb, CDK4, TNFα, IFNα, and IFNγ were upregulated during early infection with the virus (3d post-infection) alone but not at 7 days post-infection." (PMID 38279262, 2024). "We next asked how infection-induced epithelial changes impact the IEC transcriptome and drew upon a single-cell RNA sequencing (scRNA-seq) data set from our laboratories that compared transcriptomes in IECs of maCp-infected and uninfected Ifnγ−/− mice." (PMID 38995074, 2024). "IFNα, IFNβ, and Universal type I IFN treatment decreased infection in the non-targeting cells while IFNγ had no significant impact." (PMID 39678349, 2024). "Single deletion of either GRA16 or GRA24 did not result in significantly altered LDH release response to IFNγ post infection compared to the WT." (PMID 39292011, 2024). "It is believed that immunological dysregulation is induced by viruses such as the herpes viruses through the infection of T-cells, leading to an excessive production of TNF-a and IFNγ, increased macrophage activation, sustained activation of CTLs, and, finally, aggressive hyperinflammatory syndrome." (PMID 39189243, 2024). "Symptomatically infected children also showed lower S+ MBCs and T cell responses at month 3 as demonstrated by lower secretion of IFNγ and IL-2 in the cytokine release assay than those without symptomatic infection." (PMID 38689059, 2024). "GBP2 co-localized with 40% of T. gondii vacuoles by two hours post-infection in BM-MoDCs treated with IFNγ or IFNγ and Pam3CSK4, but not in unstimulated or Pam3CSK4-only stimulated conditions." (PMID 38538595, 2024). "In addition, similar levels of significantly induced expression of TNFA, IFNG, and NOS2 were noted at 4 weeks post infection, compared to the uninfected control lungs." (PMID 38338937, 2024). "However, compared to Tg infected animals, HpTg infected animals only had decreased levels of MLN Ifnγ and SI2 Il-10 at day 5 post Tg infection, despite increased Il-4 and Il-13 in the SI, PP, MLN and SPL." (PMID 38950025, 2024). "Although T. gondii infections induce IFNγ, it is usually not detected until 2–5 days after infection, long after N. caninum proliferation has been controlled." (PMID 39445806, 2024). "Using cervical epithelial HEp2 cells that were validated to respond homogeneously to physiologically relevant levels of IFNγ, we observed reduced expression and activation of both STAT1 and its kinase JAK2 at early stages of infection, with concomitant reduction in expression of ISGs." (PMID 39194253, 2024). "While heavy exposure to Mycobacterium tuberculosis often results in latent TB latent infection (LTBI), subpopulations exist that are either resistant to infection or contain Mtb with interferon-gamma (IFNγ)-independent mechanisms not indicative of LTBI." (PMID 39162406, 2024). "The blockade of TIM-3 signaling in spleen lymphocytes from S. japonicum infected mice by treatment with soluble TIM-3-Fc fusion protein increased the population of CD4+IFNG+ Th1 cells, suggesting that TIM-3 signaling suppresses Th1 cell activity during infection." (PMID 38979184, 2024). "Neither IFNγ nor IL-10 blockade had a substantial impact on the expansion of NK cells or their function after infection." (PMID 38950078, 2024). "More recently, it was demonstrated that during infection, the epithelial-derived IL18 synergized with IL12 produced by activated dendritic cells (DCs) to stimulate innate lymphoid cell 1 (ILC1) production of IFNγ required for early parasite control." (PMID 38756777, 2024). "Infection with the H7N7 resulted in increased levels of CCL2, IFNγ, IL1β, IL-6, and TNFα in the brains of mice, whether or not they had been previously vaccinated." (PMID 37063291, 2023).
infection (continued). "In this current study the influence of IL-4- and IFNγ-dependent polarisation (pre-stimulation) or stimulation of non-polarised (post-stimulation) macrophages upon infection with Salmonella enterica serovar Typhimurium was analysed." (PMID 37190073, 2023). "At week 4 post infection, CD4+ T-cells showed a mixed response to S. mansoni AWA by secreting cytokines which encompassed Th1 (IFNγ, TNFα, IL-2 & IL-1β), Th2 (IL-4, IL-5, IL-13) and regulatory responses (IL-10) as well as the regulatory T cell transcription factor Foxp3." (PMID 37837930, 2023). "In these experiments, mean control infection levels in the absence of IFNγ were 11% for HeLa, 20% for HFF, and 18% for THP1." (PMID 37975677, 2023). "A degree of co-expression of genes with proposed opposing effects on M.tb, e.g., IL1B and IFNG (better control) versus IDO1 and Type 1 IFNs (reduced control) – suggests counteracting influence on growth during the early phase of infection and requires further experimentation." (PMID 37333188, 2023). "IL-27, like IFNγ, reduced MCMV production in macrophages 72h post-infection." (PMID 37153622, 2023). "Interestingly, the frequencies of IFNγ and TNF-producing NP-specific T cells in the BAL were superior to the ones observed after natural infection, confirming the potent adjuvant effect of IL-1β on local TRM formation in pigs." (PMID 37153548, 2023). "The enhanced production of IFNγ and of several of its anti‐microbial target genes between day 7 and 11 after infection may explain the ability of Acod1−/− mice to resolve NMII infections despite an initial increase in bacterial replication." (PMID 36479617, 2023). "To address whether inflammation-mediated activation of BBB endothelial cells is a prerequisite for infection by SARS-CoV-2, we stimulated EECM-BMEC with the pro-inflammatory cytokines TNFα/IFNγ prior to infection." (PMID 37875964, 2023). "While IFNγ is vital for host defense against Mtb, Type I IFN (IFN-I) signaling promotes infection." (PMID 37965344, 2023). "Indeed, challenge infection with Tc led to significant expansion of effector CD4+ and CD8+ T cells and production of cytotoxic molecules (IFNγ, PRF1, GZB) by both CD4+ and CD8+ effector T-cell subsets in vaccinated (vs. non-vaccinated) pregnant mice." (PMID 38104118, 2023). "Treatment of adiponectin during infection did not affect IFNγ and IL-17 cytokine production but enhanced IL-13 secretion levels in small intestinal tissues." (PMID 37635188, 2023). "We noted a significant apical increase in IFNγ in the co-cultures in the absence of any stimulation or infection." (PMID 37006263, 2023). "Crossing data from infections during the Delta-Omicron wage, with both T cell and B cell responses after two doses of SARS-Cov-2 vaccines, we performed a ROC curve analysis for the levels of anti-SP IgG antibodies and SARS-CoV-2-induced IFNγ secretion." (PMID 37606852, 2023). "The immune response to Mtb is characterized by a massive influx of immune cells in an attempt to control infection, primarily macrophages and CD4+ T cells, followed by an overwhelming production of cytokines and chemokines, namely tumor necrosis factor (TNF) and interferon-gamma (IFNγ)." (PMID 37274195, 2023). "Infection with S. mansoni had no impact on H1-specific or anti-CD3-induced production of IFNγ, IL-17, and of IL-10 from draining inguinal lymph nodes." (PMID 36753434, 2023). "However, in two rat studies with Haemophilus influenzae meningitis induced by intraperitoneal injection, it was shown that both in serum and in cerebrospinal fluid, ACAAs against IFNγ and tumor necrosis factor (TNF)-α were induced during the infection." (PMID 38203686, 2023). "At day 10 post-infection, the majority of CD8 MHCI tetramer+ cells in the lung were Ifnγ+." (PMID 37842651, 2023). "At 3 d post-infection, the cytokines interferon gamma (IFN-γ), IL-6, MCP-1, and TNF-α were significantly reduced in TgΔLOXL1-infected mice, which prompted us to examine TgΔLOXL1 in IFN-γ KO mice." (PMID 37646522, 2023).